IGF1 (insulin like growth factor 1)
Diseases named in the same sentence as IGF1 in open-access papers (continued):
Sharing a sentence is not in itself a finding about the gene and the disease.
breast cancer (continued). "IGF-1 can not only stimulate the growth of breast epithelial cells and fibrositis components but also interact with oestrogen and increase the aggressiveness of breast cancer cells, thus increasing the risk of breast cancer in premenopausal women." (PMID 38378562, 2024). "While childhood height may be linked to breast cancer through growth-regulating hormones, such as insulin-like growth factor-1, lower breast density may mediate the association between excess childhood adiposity and breast cancer risk." (PMID 38335218, 2024). "Moreover, increased serum level of insulin-like growth factor (IGF) 1 was also a risk factor for BC because IGF-1 had a potential synergistic effect with estrogen in milk in breast cancer development." (PMID 39285863, 2024). "Considering height and IGF-1 and their association with CRC risk and breast cancer risk, IGF-1 remained significantly associated with breast cancer risk (ORMVMR = 1.06, PMVMR = 0.049), while height remained significantly associated with colorectal cancer risk (ORMVMR = 1.06, PMVMR = 0.045)." (PMID 38527997, 2024). "Similarly, elevated serum levels or increased expression of IGF-1 has been implicated in the development of various non-breast cancers." (PMID 36331687, 2023). "There are several complex causes possibly involved in the association of diabetes with breast cancer, including hyperglycemia, insulin signaling, insulin‐like growth factor 1 (IGF‐1) signaling, and regulation of endogenous sex hormones, which further increases the risk of breast cancer." (PMID 37095062, 2023). "In addition, high levels of blood glucose, insulin, and insulin-like growth factor 1 (IGF-1) have been associated with an increased risk of breast cancer." (PMID 37509485, 2023). "Furthermore, recent Mendelian randomization studies confirmed the potential causal associations between IGF-1, testosterone and breast cancer risk." (PMID 38000092, 2023). "The association between IGF-1 and the risk of breast cancer has been reported in previous studies, which might be explained by its role in stimulating cancer cell proliferation, inhibiting apoptosis, and promoting angiogenesis." (PMID 38000092, 2023). "Prospective analyses suggest an association between circulating IGF1 and breast cancer risk." (PMID 37686596, 2023). "The finding of lower adult IGF-1 in response to larger body size during childhood may be a part of the mechanism through which early life adiposity influences breast cancer risk." (PMID 35396499, 2022). "In addition to sex hormones, we also confirmed several other biomarkers to be associated with breast cancer, such as waist circumference, BMI and IGF-1." (PMID 35578620, 2022). "Circulating concentrations of IGF-1 AND IGFBP-3 are associated with breast cancer risk." (PMID 36672557, 2022). "However, the importance of IGF-1R-specific functions in breast cancer is supported by the fact that an IGF-1-driven gene signature is associated with poor disease outcomes." (PMID 36556357, 2022). "Besides, IGF-1 is linked to regulating mitochondrial biogenesis and mitophagy, which promote mitochondrial protection in normal liver tissue and breast cancer cells." (PMID 35334906, 2022). "Increased childhood body size was associated with a reduction in IGF-1 (effect size per standard deviation, −0.24, 95% confidence interval: [−0.33: −0.15]), while IGF-1 had a positive effect on breast cancer risk (odds ratio per standard deviation, OR, 1.08 [1.03: 1.15])." (PMID 35396499, 2022). "For example, body fatness during childhood may protect against breast cancer risk through hormonal pathways (e.g., IGF-1, oestradiol, testosterone, SHBG17,18)." (PMID 35396499, 2022). "Mechanistically, testosterone and insulin mediated 21% and 35%, respectively of the total, genetically determined association of BMI with endometrial cancer risk whilst HDL cholesterol and IGF-1 mediated 40% and 22%, respectively of the association between BMI and breast cancer risk." (PMID 36558416, 2022).
breast cancer (continued). "In 2020, a study investigated 206,263 women in the UK Biobank and revealed that high level IGF-1 in circulation could induce 40% increased risk for breast cancer in women older than 50 years old." (PMID 35250656, 2022). "Most breast cancer cells express IGF1 receptors, and IGF1 levels might be associated with an increased BC risk." (PMID 35276833, 2022). "Higher levels of energy and protein intake, as well as milk and meat consumption, are associated with elevated IGF-1 levels, which may increase the risk of developing prostate cancer in men and breast cancer in women." (PMID 34444753, 2021). "Breast cancer risk increased by 1.05 for every additional genetically predicted 5 nmol/L of IGF-1." (PMID 33557137, 2021). "Additionally, IGF-1 and estradiol has been shown to co-regulate the expression of a set of genes associated with breast cancer outcome." (PMID 33816477, 2021). "Interestingly this study also reported a positive association between genetically predicted IGF-1 concentrations and breast cancer risk however this was only in ER+ tumours." (PMID 33816477, 2021). "Four proteins including C-peptide, insulin (INS), insulin-like growth factors (IGFs) and IGF-binding proteins (IGFBPs) are taken multiple biological roles in the insulin-IGF-1 axis, one of the potential biological mechanisms underlying the obesity-breast cancer connections." (PMID 33859244, 2021). "Multiple studies have reported a positive association between IGF-1 and breast cancer." (PMID 33557137, 2021). "With few exceptions, there exists limited data regarding whether IGF-1/IGFBP-3 biomarkers may be associated with cancer in women at high risk of breast cancer." (PMID 33092613, 2020). "IGF-1, produced by adipocytes and essential for normal mammary gland growth and development, has also been implicated as a mechanistic link between obesity and breast cancer development." (PMID 32736587, 2020). "Similar to IGF-1, insulin is also a mitogen and plays a significant role in breast cancer, and this might be related to underlying insulin resistance." (PMID 32528752, 2020). "Cox proportional hazards models were used to calculate hazard ratios (HRs) and 95% confidence intervals (CIs) for all-cause mortality, breast cancer-specific mortality, and breast cancer recurrence associated with different levels of IGF1 and other biomarkers with multivariable adjustment." (PMID 32974138, 2020). "Besides breast cancer risk, insulin and IGF-1 levels have been positively connected to recurrence and mortality." (PMID 30634494, 2019). "The association of the IGF1 system with breast cancer development has been firmly established." (PMID 31771180, 2019). "Alcohol use is positively associated with mammographic density and with breast cancer risk in the general population, likely due to its stimulatory effect on circulating estrogens and IGF-1 levels, which may increase dense epithelial cell proliferation." (PMID 31242899, 2019). "Dysregulation of a number of pathways has been hypothesized to mechanistically link obesity with increased risk of breast cancer recurrence in humans, including changes in circulating adipokines, insulin/IGF-1, sex hormones, and chronic inflammation." (PMID 30867005, 2019). "Indeed, a pooled meta-analysis of nested case-control studies found a relative risk of 1.2 for breast cancer risk comparing top to bottom categories of IGF-1 levels." (PMID 31816813, 2019). "Thus, while there is an association between SNPs in the core IGF-1 signalling genes and BW, our data do not provide any evidence that higher BW as predicted by these two IGF pathway SNPs is associated with adult breast cancer risk." (PMID 30737679, 2019). "Also hyperglycemia seems to increase the risk of breast cancer in pre-malignant cells and to enhance cancer progression in malignant epithelial cells through leptin/IGF1 signaling." (PMID 31380268, 2019).
breast cancer (continued). "However, increased expression of IGF-1R and/or IGF-1 is associated with various types of cancers, notably in breast cancer, in which breast cancer cells often coexpress IGF-1R and ERα." (PMID 30692633, 2019). "High birthweight first pregnancies may increase breast cancer risk, possibly through the association of birthweight with oestrogen and insulin-like growth factor 1 levels." (PMID 30286782, 2018). "Biological mechanisms that may underlie the association between obesity and breast cancer include altered sex hormone metabolism, adipokine signaling, subclinical inflammation, hyperglycaemia, hyperinsulinaemia, and increased IGF-1 signaling." (PMID 29855282, 2018). "Indeed, not only have biomarkers like estrogen, insulin, and IGF-1 been implicated in breast cancer development/recurrence but, more recently, myokines have been observed important to breast cancer development." (PMID 29880779, 2018). "For example, birthweight is positively associated with higher breast density and breast cancer risk in previous studies and these associations are explained by higher insulin-like growth factor 1 (IGF-1) levels during adulthood in women with greater birthweight." (PMID 28851411, 2017). "Interestingly several X10/IGF1-enriched mutations were observed, including Ezh2, Hras, and Traf7, of which Ezh2 and Hras are prominent modulators of human breast cancer." (PMID 28173837, 2017). "These properties of insulin and IGF1 could underlie increased growth of breast cancer in obesity and of osteosarcoma in puberty." (PMID 28316059, 2017). "Elevated levels of IGF-1, in particular, have been associated with increased risk of breast cancer." (PMID 28865460, 2017). "The pre‐existing metabolic differences in normal breast epithelium and elevated levels of cytokines (e.g., IGF1 and TNFα) may determine susceptibility to oncogenic transformation and thereby increase breast cancer risk in some women." (PMID 28369883, 2017). "We tested IGF1 as a potential host‐factor that could affect cellular bioenergetics, because IGF1 is known to be associated with breast cancer risk." (PMID 28369883, 2017). "Moreover, we also compared our compound 2-induced gene expression alterations in tumor cells with a published gene signature associated with IGF-1 response in breast cancer cells." (PMID 27384680, 2016). "Similarly, high IGF-1 is associated with increased breast cancer risk in both premenopausal women (comparison of highest to lowest quintile, odds ratio (OR) = 1.2 (95% CI, 1.0–1.5)) and postmenopausal women (OR = 1.33 (95% CI, 1.1–1.6))." (PMID 27338371, 2016). "High levels of IGF1 and insulin in humans have been linked to increased risk of breast cancer." (PMID 27255182, 2016). "Additionally, epidemiologic studies have shown a relation between high circulating IGF-1 levels, breast density, and risk of breast cancer (BC)." (PMID 26738606, 2016). "Genetic variants of insulin-like growth factor 1 (IGF1) pathway genes have been shown to be associated with breast density and IGF1 levels and, therefore, may also influence breast cancer risk via pro-survival signaling cascades." (PMID 27376028, 2016). "Thus far, epidemiological evidence overall suggests a positive association between IGF‐1 and breast cancer risk, particularly in premenopausal women." (PMID 27734632, 2016). "In the European group, the minor A-allele of three IGF1 SNPs (rs1549593, rs1019731, and rs12821878) was associated with decreased risk of breast cancer, but only two of these SNPs passed adjustment for the FDR: rs1019731 (OR = 0.67, 95% CI: 0.53–0.84) and rs12821878 (OR = 0.73, 95% CI: 0.61–0.88)." (PMID 27376028, 2016). "Beyond breast cancer risk, insulin and IGF-1 stimulate cancer progression and invasion." (PMID 27338371, 2016). "They hypothesized a functional interaction between the BRCA genes and IGF-1 systems, which may be causal for a higher penetrance of breast cancer in those with elevated IGF-1 levels." (PMID 27473440, 2016).
breast cancer (continued). "Similarly, the IGFBP3, IGF1R, IRS1, and PI3KCB genes have a purported relationship with breast cancer risk due to either their role in IGF1 signaling regulation, or association with strong breast cancer risk factors." (PMID 27376028, 2016). "Four highly linked IGF1 SNPs (rs2288378, rs17727841, rs7136446, and rs7956547) were modified by menopausal status among East Asian women only and associated with postmenopausal breast cancers." (PMID 27376028, 2016). "One study suggests that positive associations between IGF1 concentrations and breast cancer risk may be restricted to ER+ tumors, which may explain why stronger associations were observed for ER+ and/or PgR+ tumors in our study." (PMID 27376028, 2016). "An association between SNPs of the IGF1 pathway and breast cancer risk has been hypothesized due to the role of circulating IGF1 levels and the IGF1 signaling pathway in risk of breast cancer." (PMID 27376028, 2016). "Polymorphisms of IGF-1 and IGFBP-3 and environmental factors may work together to influence insulin-like growth factor (IGF) levels and thus breast cancer (BC) risk." (PMID 27631779, 2016). "IGF-1 is a point of convergence for major signaling pathways implicated in breast cancer growth." (PMID 25743390, 2015). "Furthermore, increased IGF-1 has been associated with increased breast cancer risk, mammographic density (especially in premenopausal women), and alcohol consumption." (PMID 25777420, 2015). "In analogy with the pathogenesis of prostate cancer, increased milk-derived IGF-1 signaling may disturb regular mammary gland morphogenesis enhancing the risk of breast cancer later in life." (PMID 26225961, 2015). "Circulating serum IGF-1 levels, which are upregulated during puberty and by milk consumption, have been related to mammographic density, a well-known risk factor of breast cancer." (PMID 26225961, 2015). "Mammographic density is one of the strongest predictors of breast cancer development and may be associated with serum IGF-1 levels in premenopausal women." (PMID 25743390, 2015). "Much of the association was limited to premenopausal women, particularly among those with high circulating IGF-1 and low IGFBP-3 levels, suggesting that vitamin D may modulate MD and breast cancer risk via IGF signaling." (PMID 28480224, 2015). "It is of interest to understand how body weight, a potentially modifiable lifestyle factor, is related to IGF-1 and sex-steroid hormone concentrations given their independent associations with breast cancer risk and the increasing prevalence of obesity in developing countries." (PMID 26352264, 2015). "Increased circulating IGF1 level is associated with an increased risk of breast cancer." (PMID 26512648, 2015). "A pooled data analysis of seventeen prospective studies from twelve countries by the Endogenous Hormones and Breast Cancer Collaborative Group showed a clear association between circulating IGF-1 and BrCa risk in Estrogen Receptor positive (ER+) tumors independent of IGFBP3 and menopausal status." (PMID 25743390, 2015). "Hence, we wanted to investigate if the Cyr61 levels played a role in pAkt overexpressing breast cancer cells, and to elucidate mechanisms associated with the IGF-1 axis and Cyr61 induced cell invasion." (PMID 25062088, 2014). "We have previously reported that obese ovariectomized mice implanted with syngeneic mouse mammary tumor cells displayed enhanced mammary tumor development and progression, and this was associated with elevated levels of bioavailable IGF-1 and downstream PI3K/Akt/mTOR signaling." (PMID 23880059, 2013). "Notably, there was a large increased relative risk of 7.3 for developing breast cancer in premenopausal women who were in the top tertile for high serum IGF-1 concentrations and had low circulating IGFBP3 concentrations." (PMID 23983688, 2013).
breast cancer (continued). "In addition, IGF-1 levels have been associated with a number of breast cancer risk factors, including birth weight, childhood body size, and mammographic density." (PMID 22414675, 2012). "IGF-1 has long been implicated in tumorigenesis as well as specifically in proliferation, survival and migration of tumor cells, with positive correlation to breast cancer progression." (PMID 22860018, 2012). "High concentrations of circulating IGF1 can increase the risk of breast cancer." (PMID 23213569, 2012). "Our findings that insulin-like growth factor 1 (IGF-1) is down-regulated in the parous breast is consistent with published data reporting overall lower levels of IGF-1 in parous than in nulliparous women and support the association of IGF1 with increased breast cancer risk." (PMID 23057841, 2012). "High IGF-1 activation was also associated with poor prognosis in breast cancer." (PMID 22415797, 2012). "Circulating IGF-1 levels were associated with primary breast cancer risk." (PMID 22415797, 2012). "Moreover, the IGF-1/IGF-1 receptor axis has also been shown to be involved in the increased risk of early-onset breast cancers in women with mutations in the Breast Cancer Susceptibility gene (BRCA1)." (PMID 21888628, 2011). "Additionally, as in human BRCA1-associated breast cancer, increased expression of several components of the IGF axis is seen in liver, normal mammary tissue and mammary tumors of these mice along with increased levels of IGF-1 in serum." (PMID 21888628, 2011). "Our data provide evidence that the IGF-1/IGF-1R signaling axis may play a causal role in antiestrogen resistance of breast cancer cells, despite continuous suppression of ER transcriptional function by antiestrogens." (PMID 21595894, 2011). "Although IGF-1 signaling in breast cancer has been primarily associated with paracrine activity, endocrine sources of IGF-1 may also have a role in breast cancer." (PMID 21535875, 2011). "Indeed there is a strong positive association between IGF-1 levels and breast cancer, especially among premenopausal women." (PMID 21535875, 2011). "Analysis of the SNPs in IGF1 did not reveal any significant associations with any of the parameters studied (IGF1, IGFBP3, IGFratio or mammographic density), and thus we were unable to verify the previous findings regarding these SNPs and association to IGF1 levels and breast cancer risk." (PMID 20302654, 2010). "Some, but not all, subsequent prospective studies have supported a positive association between IGF1 and breast-cancer risk, but have been inconsistent as to whether the association differs according to menopausal status." (PMID 20472501, 2010). "It is therefore important to examine whether the association of IGF1 with breast-cancer risk varies according to the oestrogen-receptor status of the tumour or circulating concentrations of oestradiol." (PMID 20472501, 2010). "Circulating IGF1 is positively associated with breast-cancer risk." (PMID 20472501, 2010). "The influence of endogenous hormones on the risk of breast cancer of women may involve in addition to estrogens effects of progesterone, prolactin, testosterone and IGF-1 on terminal differentiation of mammary stem cells." (PMID 19738607, 2009). "In particular, IGF-1 is a strong mitogen, and varying levels of free IGF-1 between E+P and E-alone treatment could help explain the increased risk of breast cancer with E+P." (PMID 20034393, 2009). "Higher circulating IGF-1 level was associated with higher risk of prostate cancer, lung cancer, colorectal cancer, premenopausal breast cancer and younger aged ovarian cancer." (PMID 18781172, 2008). "IGF-1 levels, which could track through life, have been associated with breast cancer risk, particularly premenopausal breast cancer risk." (PMID 18827810, 2008).